PAK2 (p21 (RAC1) activated kinase 2)
Diseases named in the same sentence as PAK2 in open-access papers (continued):
Sharing a sentence is not in itself a finding about the gene and the disease.
gastric cancer (continued). "The aim of this study was to investigate whether PAK2 expression and its phosphorylation status are correlated with tumor progression and prognosis in gastric cancer." (PMID 24621074, 2014). "Furthermore, cox multi-factor analysis showed that PAK2 (p = 0.012) and pSer20PAK2 (p = 0.010) were independent prognosis factors for human gastric cancer." (PMID 24621074, 2014). "The overexpression of PAK2 and pSer20PAK2 proteins may be recognized as independent prognostic markers for overall survival, therefore, the detection of these proteins may be helpful for predicting clinical outcome for patients with gastric cancer." (PMID 24621074, 2014). "PAK2 was a necessary interaction partner of ARHGDIB, and knockdown of PAK2 greatly reduced ARHGDIB-induced cell invasion and ARHGDIB-mediated chemoresistance in gastric cancer, and loss of SATB1 in lung cancer has been shown as a possible marker for poor survival." (PMID 24369726, 2013). "CDK12, a gene that drives the growth of gastric cancer in humans, triggers the MAPK signaling pathway by directly binding to and phosphorylating PAK2 at T134/T169, which promotes tumor development and cell division." (PMID 39769207, 2024). "Gastric cancer progression is highly correlated with the MAPK signalling pathway, and CDK12 can affect this pathway by phosphorylating the PAK2 gene, leading to the metastasis of gastric cancer." (PMID 38503865, 2024). "In gastric cancer cells, CDK12 phosphorylates PAK2 for activation of the MAPK signaling, and its specific inhibitor Proterol has been approved for clinical trials by the FDA due to positive outcomes obtained from PDX and cell line studies." (PMID 36769170, 2023). "Finally, based on the expression data of four gene markers (DACT1, EZH2, PAK2, PSPC1), we constructed a staging prediction model for 953 gastric cancer samples (319 early, 497 intermediate, and 137 advanced)." (PMID 40959076, 2025). "PAK2 plays an important role in tumor aggressiveness, but its involvement in gastric cancer has not yet clear." (PMID 24621074, 2014). "However, the clinical significance of the activation of PAK2 in human gastric cancer has not been fully elucidated." (PMID 24621074, 2014).
ovarian carcinoma (13 papers, 2011 to 2025). A malignant neoplasm originating from the surface ovarian epithelium. "In agreement, repression of miR-134 and consequent upregulation of PAK2 contributed to paclitaxel resistance in these ovarian cancer cells." (PMID 29362401, 2018). "As PAK2 is involved in motility, it should be further explored as a pro-metastatic gene in ovarian cancer." (PMID 25050916, 2014). "A study cited that prostasin, a trypsin-like serine peptidase produced in epithelial cells, may be a viable target for the treatment or repression of some ovarian cancers by altering the CASP/PAK2-p34 pathway." (PMID 39769207, 2024). "PAK2 promotes paclitaxel resistance in ovarian cancer mediated through p34/MLCK signaling." (PMID 36830998, 2023). "Authors concluded that both, the miR-134 and its target PAK2 might be a potential target for therapeutic intervention of ovarian cancer paclitaxel resistance." (PMID 35501919, 2022). "Overexpression of PAK1 and PAK2 has been found in ovarian cancer cells." (PMID 35501919, 2022). "In addition, miR-134 was shown to mediate Bad phosphorylation, and affected cell survival and apoptosis by targeting PAK2 in ovarian-cancer cells." (PMID 29362401, 2018). "PAK2 increases the motility of ovarian cancer cells by enhancing breakdown of collagen type I." (PMID 28707321, 2017). "Knockdown of Pak1 and Pak2 in ovarian cancer cell lines reduced cell migration and invasion." (PMID 25050916, 2014). "We identified Pak2 as a possibly important mediator of ovarian cancer cell migration on ECM." (PMID 25050916, 2014). "PAK2′s role in chemoresistance (e.g., HNC and ovarian cancer) suggests it as a potential therapeutic target." (PMID 39769207, 2024). "RT-qPCR analysis revealed that URI1, PAK2, PARP1, CLU, and TIMP3 were significantly upregulated, while UBB, RPL11, CAV1, NUPR1, and Hsp90ab1 were significantly downregulated in the ovarian cancer samples." (PMID 37124501, 2023). "We also found that apoptosis-related genes, URI1, PAK2, PARP1, CLU and TIMP3, were highly expressed, while immune-related genes, UBB, RPL11, CAV1, NUPR1 and Hsp90ab1, were lowly expressed in ovarian cancer cells." (PMID 37124501, 2023). "In conclusion, our results indicate that FN and COLL affect the motility of the selected ovarian cancer cells lines and the effect of COLL is likely mediated, at least in part, by PAK2." (PMID 25050916, 2014). "Another study revealed that RP11-499E18.1 may have tumor suppressor functions by lowering the nuclear translocation of p-SOX2 and dissociating the relationship between PAK2 and SOX2 in ovarian cancer." (PMID 39769207, 2024).
prostate carcinoma (13 papers, 2014 to 2025). A carcinoma that arises from epithelial cells of the prostate gland. "Altered PAK1 expression was associated with reduced survival in skin and prostate cancers, while PAK2 alterations were linked to poor outcomes in pancreatic cancer." (PMID 39756822, 2025). "Elevated PAK1 protein levels are associated with colorectal, hepatocellular, and prostate cancer metastasis, and PAK2 and 6 overexpression is linked to chemotherapeutic and radiation resistance in breast and prostate cancers, respectively." (PMID 29875996, 2018). "Notably, a study cited that binding of α2-macroglobulin to the cell surface-associated (GRP78) receptor in 1-LN prostate cancer activates PAK2, causing the phosphorylation of LIMK." (PMID 39769207, 2024). "This csHSPA5-dependent activation of PAK-2 leads to cell proliferation and the overall survival of prostate cancer cells." (PMID 41301006, 2025). "In prostate cancer, csHSPA5 binds to α2-macroglobulin (α2M), a known proteinase inhibitor, to phosphorylate and activate PAK-2, a known mediator of angiogenesis, migration, and metastasis." (PMID 41301006, 2025). "In prostate cancer, PAK2 enhances tumor plasticity by regulating SRY (sex-determining region Y)-box 2 (SOX2) expression, contributing to castration-resistant progression." (PMID 39769207, 2024). "PAK2 has emerged as a significant regulator in prostate cancer (PCa) progression, particularly in the transition from androgen-dependent to androgen-independent stages." (PMID 39769207, 2024). "PAK2 was the most frequently altered gene (4%) in prostate cancer." (PMID 39756822, 2025). "Similarly, PAK2 amplifications in lung and prostate cancers suggest its involvement in dysregulated growth factor signaling pathways, such as the PI3K/AKT and MAPK pathways, which are commonly activated in these malignancies." (PMID 39756822, 2025). "One would expect this research pool to be larger, as there are a number of—at least what appears to be—intuitive reasons to study PAK2′s role in prostate cancer development, including the gene’s involvement in actin dynamics, cell survival, and cell proliferation." (PMID 39769207, 2024). "Interestingly, PAK2 was found to be more active in castration-resistant prostate cancers compared to castration-sensitive cancers and to contribute to prostate cancer cell invasion as well as proliferation in vitro." (PMID 29510700, 2018). "Interestingly, elevated levels of PAK2 were found in phosphoproteomic analysis of castration resistant prostate cancer and knockdown experiments demonstrated that PAK2 regulates prostate cancer cell invasion." (PMID 30220968, 2018). "Another previous study reported that GRP78 led to the activation of PAK-2 and LIMK1 to accelerate the metastasis in prostate cancer." (PMID 29849883, 2018).
autism (12 papers, 2020 to 2025). Persistent deficits in social interaction and communication and interaction as well as a markedly restricted repertoire of activity and interest as well as repetitive patterns of behavior. "Moreover, Pak2 haploinsufficiency caused a decrease in synapse densities, defective long-term potentiation, and autism-related behaviors in mice, but also alterations in actin polymerization." (PMID 40943146, 2025). "Moreover, PAK2+/− mice display decreased synapse densities, defective long-term potentiation, and autism-related behaviours, and PAK2 nonsense mutations and deletions that impaired the PAK2 function have been found in large cohorts of patients with ASD." (PMID 36899941, 2023). "Clinically, loss-of-function mutations of human PAK2 gene result in autism where an accelerated white matter maturation and hypermyelination are observed in the brain compared with healthy controls, suggesting that PAK2 may inhibit OPC terminal differentiation." (PMID 40586933, 2025). "PAK2 is important for brain development, and its haploinsufficiency leads to autism-related behavior and its inhibition partially restores several synaptic fragile X syndrome phenotypes in the Fmr1 KO mice." (PMID 36292679, 2022). "For example, we found that PAK2 haploinsufficiency resulted in autism-related behaviors in both mice and humans." (PMID 33306168, 2022). "In addition, PAK2/Pak within 3q29, TBX1/org-1 within 22q11.2, autism-associated CHD8/kis, and microcephaly-associated ASPM/asp also showed smaller wing areas and vein lengths." (PMID 32579612, 2020). "PAK2 haploinsufficiency will lead to significant decreased synapse densities, defective long-term potentiation, and autism-related behaviors by regulating actin cytoskeleton dynamics in mice, indicating that PAK2 plays a key role in brain development and autism pathogenesis." (PMID 33796531, 2021). "Moreover, our recent study indicated that PAK2 dysfunction resulted in decreased synapse densities, attenuated LTP, and autism-related behaviors in mice." (PMID 33306168, 2022). "PAK2 haplo-insufficiency has also been reported in ASD patients and PAK2 heterozygous mice exhibited a marked decrease in synapse density and impaired LTP, as well as autism-relevant behaviours that were related to reduced activity of LIMK1 and subsequent activation of cofilin." (PMID 34440848, 2021).
pancreatic cancer (10 papers, 2020 to 2026). "ADAM9 and PAK2 showed high expression in pancreatic cancer and strong associations with tumor proliferation, invasion, and immune regulation." (PMID 42131338, 2026). "In pancreatic cancer, PAK2 and PAK4 alterations were linked to significant differences in survival outcomes." (PMID 39756822, 2025). "Upon intersection, we identified 23 metabolic pathways implicated in PAK2-promoted pancreatic cancer liver metastasis, comprising 5 upregulated and 18 downregulated metabolic pathways." (PMID 38343537, 2024). "The association of PAK2 with pancreatic cancer hematogenous metastasis was confirmed in our TCGA dataset analysis." (PMID 38343537, 2024). "Regardless, this set of results seems to suggest that the TGF-β signaling pathway is the key route through which PAK2 works to cause pancreatic cancer." (PMID 39769207, 2024). "In this study, we hypothesize that the NCOA family is implicated in the process of pancreatic cancer liver metastasis regulated by PAK2, although the specific mechanism requires further investigation." (PMID 38343537, 2024). "In conclusion, the further development of spatial transcriptomics data and other sequencing technologies may offer deeper insights into the mechanisms underlying PAK2 in the process of pancreatic cancer liver metastasis." (PMID 38343537, 2024). "Amplifications in PAK1 and PAK2 were particularly prevalent in breast, lung, prostate, and pancreatic cancers, reinforcing their roles in tumorigenesis." (PMID 39756822, 2025). "In pancreatic cancer cells, substantial evidence supported the involvement of PAK2 in the regulation of 90 transcription factors, including 72 positive regulators and 18 negative regulators." (PMID 38343537, 2024). "After determining the differentiation starting point using the same method, we found compelling evidence confirming that PAK2 promoted the low differentiation of pancreatic cancer cells." (PMID 38343537, 2024). "ROC analysis indicated good discriminative ability of PAK2 for pancreatic cancer liver metastasis in the GSE19279 cohort (AUC=0.73) and GSE71729 cohort (AUC=0.7)." (PMID 38343537, 2024). "We categorized pancreatic cancer tissues from the TCGA cohort into low and high PAK2 expression groups according to the median PAK2 expression." (PMID 38343537, 2024). "Through a series of algorithmic filters, we identified PAK2 as a key gene promoting pancreatic cancer liver metastasis." (PMID 38343537, 2024). "In the GSE15471, GSE62165, GSE62452, and GSE71729 cohorts, the Wilcoxon test showed statistically significant differences in PAK2 expression between pancreatic cancer and normal individuals, with elevated expression of PAK2 in pancreatic cancer patients." (PMID 38343537, 2024). "In this investigation, we explored the influence of PAK2 on the differentiation and development of pancreatic cancer cells." (PMID 38343537, 2024). "We confirmed the significance of PAK2 across multiple datasets and databases, investigating its implications in the initiation and advancement of pancreatic cancer." (PMID 38343537, 2024). "There is limited research on the relationship between PAK2 and pancreatic cancer, and existing studies have only demonstrated, at the cellular experimental level, that PAK2 can increase the proliferation and invasive capabilities of pancreatic cancer cells." (PMID 38343537, 2024). "Pseudo-temporal analysis revealed a significant correlation between PAK2 expression and the lower differentiation status of pancreatic cancer cells." (PMID 38343537, 2024). "The migration area in the experimental group was notably lower than that in the control group, underscoring that PAK2 knockdown hampers the migration of pancreatic cancer cell lines PANC-1 and Bx-PC3." (PMID 38343537, 2024).
pancreatic cancer (continued). "CCK8 experiments showed that silencing PAK2 led to a decrease in the proliferative capacity of pancreatic cancer cells and scratch experiments demonstrated that low expression of PAK2 decreased invasion capability in pancreatic cancer cells." (PMID 38343537, 2024). "Elevated PAK2 levels are common in pancreatic cancer, where elevated levels of the protein activate the TGF-β signaling, which promotes the epithelial–mesenchymal transition process." (PMID 39769207, 2024). "Applying a similar approach to assess PAK2 high-expression cells and PAK2 low-expression cells, we observed that PAK2 triggered the upregulation of 17 metabolic pathways and the downregulation of 25 metabolic pathways in pancreatic cancer cells." (PMID 38343537, 2024). "The results showed that increased expression of PAK2 reduces the sensitivity of pancreatic cancer to gemcitabine treatment." (PMID 38343537, 2024). "In our study, we found that PAK2 is crucial for influencing the communication network of pancreatic cancer cells." (PMID 38343537, 2024). "To further explore the mechanism by which PAK2 induces gemcitabine resistance, we first identified gemcitabine resistance-related genes in pancreatic cancer based on the GSE140077 dataset." (PMID 38343537, 2024). "Evidence at the protein level, indicating PAK2’s role in mediating pancreatic cancer, was provided by the HPA database." (PMID 38343537, 2024). "Similarly, the impact of PAK2 on survival in pancreatic cancer underscores its potential role in driving the aggressive biology of this disease." (PMID 39756822, 2025). "Finally, the TGF-Beta signaling pathway was consistently upregulated in all four GSVA analyses, indicating it as the key pathway primarily regulated by PAK2 in mediating pancreatic cancer liver metastasis." (PMID 38343537, 2024). "Finally, the statistical analysis also suggests that PAK2 reduces differentiation among pancreatic cancer cells, which increases their malignancy." (PMID 39769207, 2024). "Hence, PAK2 was chosen as the pivotal gene in the progression of pancreatic cancer liver metastasis for subsequent investigations." (PMID 38343537, 2024). "Therefore, we identify the TGF-Beta signaling pathway as the key signaling pathway regulated by PAK2 in mediating pancreatic cancer liver metastasis." (PMID 38343537, 2024). "Furthermore, based on this, our study proposes that PAK2 is a key gene mediating the liver metastasis of pancreatic cancer." (PMID 38343537, 2024). "Intervening in the expression of PAK2 may offer a promising therapeutic strategy for preventing liver metastasis of pancreatic cancer and improving its prognosis." (PMID 38343537, 2024). "In summary, PAK2 emerged as a pivotal gene orchestrating pancreatic cancer liver metastasis." (PMID 38343537, 2024). "Additionally, we conducted in-depth mechanistic analysis of how PAK2 influences the process of pancreatic cancer liver metastasis and ultimately validated the findings through cell experiments." (PMID 38343537, 2024). "In addition to signaling pathways, we observed that the elevation of PAK2 was correlated with increased malignant behaviors of pancreatic cancer, such as angiogenesis (logFC=0.011, P<0.05), and epithelial-mesenchymal transition (logFC=0.01, P<0.05)." (PMID 38343537, 2024). "Thus, we preliminary concluded that PAK2 leads to a less differentiated state in pancreatic cancer cells." (PMID 38343537, 2024). "Hence, we have grounds to posit that one of the roles of PAK2 is to foster the liver metastasis of pancreatic cancer through the activation of the TGF-beta signaling pathway." (PMID 38343537, 2024). "Flow cytometry reveals that PAK2 significantly inhibited apoptosis in pancreatic cancer cell lines." (PMID 38343537, 2024).